SIRT1 (sirtuin 1)
Diseases named in the same sentence as SIRT1 in open-access papers (continued):
Sharing a sentence is not in itself a finding about the gene and the disease.
Alzheimer disease (continued). "For example, it could prevent and treat Alzheimer's Disease by regulating the mTOR signal pathway, activating SIRT1, and deacetylating histone acetylases." (PMID 35932505, 2022). "Previous studies have shown that the SIRT1 gene may play an important role in the pathophysiology of schizophrenia, bipolar disorder, and Alzheimer's disease, but the exact mechanisms are unclear." (PMID 34285334, 2021). "Activation of SIRT1 may be beneficial for the treatment of Alzheimer’s disease (AD), in which SIRT1 levels are typically reduced." (PMID 34744791, 2021). "Sirt1 may also be a protective factor in neurodegenerative diseases, such as Alzheimer’s disease, Parkinson’s disease, and ALS." (PMID 34828382, 2021). "Studies show that the intervention of AMPK/Sirt1 signaling pathway may improve neuropathological defects in Alzheimer’s disease." (PMID 34644262, 2021). "SIRT1 affects progression of Alzheimer’s disease through interactions with FOXO3a and SIRT3." (PMID 33806509, 2021). "In particular, patients with Alzheimer’s disease have reduced expression of sirtuin 1 (SIRT1)." (PMID 33171879, 2020). "Recently, Bonfili and colleagues found that the administration of the same probiotic formulation used in this study (Slab51®) significantly reduced the oxidative stress in a triple transgenic mouse model of Alzheimer’s disease, by inducing the Sirtuin-1-dependent mechanism." (PMID 32050688, 2020). "The aim was to determine whether the neuroprotective effect of SIRT1 in Alzheimer’s disease (AD), due to inhibition of aggregation of the β-amyloid peptide (Aβ), involves activation of α7 nAChR." (PMID 32003755, 2020). "Moreover, SIRT1 can ameliorate neurodegeneration in in vivo and in vitro models of Alzheimer’s disease, amyotrophic lateral sclerosis (ALS), and Wallerian degeneration, suggesting that SIRT1 is important for neuronal protection against neurotoxic insults." (PMID 30416425, 2018). "In neurological disorders such as Alzheimer disease (AD), Sirt1 is decreased." (PMID 30304806, 2018). "In addition to providing neuroprotection against cerebral ischemia, the activation of SIRT1 has been shown to confer protection against neurodegenerative diseases, such as Alzheimer's disease (AD), Parkinson's disease (PD) and Huntington's disease (HD)." (PMID 30532738, 2018). "It has been found that SIRT1 could be upregulated to antagonize neuronal injury in different animal models, such as cerebral ischemia, Alzheimer's disease (AD), and Huntington's disease (HD)." (PMID 29081884, 2017). "In addition, in an Alzheimer’s Disease model, triheptanoin in the context of a ketogenic diet increased the expression of the mRNA levels of Sirt1, Pparg, Sod1 and Sod2." (PMID 27564703, 2016). "Moreover, SIRT1 inhibits neurodegeneration in in vivo and in vitro models of Alzheimer's disease, amyotrophic lateral sclerosis (ALS), and Wallerian degeneration." (PMID 26426123, 2015). "SIRT1 overexpression is also reported to prevent microglia-dependent Aβ toxicity in Alzheimer’s diseases through inhibiting NF-κB signaling by deacetylating the lysine 310 residue of the RelA/p65 subunit of NF-κB, thereby preventing its transcriptional activity." (PMID 25247581, 2014). "Moreover, in the Huntington and Alzheimer disease models, resveratrol inhibited neuronal degeneration via SIRT1 activation." (PMID 23901250, 2013). "Furthermore, SIRT1 protects neuron from neurodegeneration in cell-based models of Alzheimer's disease, amyotrophic lateral sclerosis (ALS), and Wallerian degeneration." (PMID 19173742, 2009). "A link between SIRT1 and Alzheimer’s disease (AD) is also increasingly evident." (PMID 27713233, 2009).
Alzheimer disease (continued). "Furthermore, SIRT1 overexpression enhances neuronal protection and regulates antioxidant responses by modulating ROS, nitric oxide (NO), proinflammatory cytokine production, and Aβ expression in the brains of individuals with Alzheimer's disease." (PMID 40777747, 2025). "Additionally, several studies found that SIRT1/FoxO1 signaling could be activated by physical exercise to improve PINK1/PARKIN-mediated mitophagy in Alzheimer’s disease." (PMID 37629033, 2023). "Regulation of FOXO3a contributes to CR-induced prevention of Alzheimer’s disease and spatial memory deterioration in mouse models, and in vitro in human cells, by reducing Aβ peptides through insulin receptor-induced hyperphosphorylation and SIRT1-mediated deacetylation of FOXO3a." (PMID 33806509, 2021). "Indeed, overexpression of SIRT1 was protective against learning and memory impairment in animal models of Alzheimer’s disease and increased SIRT1 activity could promote memory processes, whereas SIRT1 knockout animals showed impaired cognitive abilities." (PMID 34206738, 2021). "As an activator of sirtuin 1 (SIRT1), resveratrol has been reported to affect many physiological processes including senescence, and many diseases including metabolic syndrome, hypertension, Alzheimer’s disease, cardiovascular diseases, and inflammatory disease." (PMID 34633989, 2021). "Moreover, SIRT1 activators, such as resveratrol, could exert protective effects in experimental model of Alzheimer disease." (PMID 30411846, 2019). "Consistent with a role for SIRT1 in brain dysfunction, animal models of ALS and Alzheimer's disease respond to resveratrol induced SIRT1 activation by both promoting α-secretase nonamyloidogenic activity and attenuating Aβ generation, a hallmark for Alzheimer's disease." (PMID 26904696, 2016). "Variants of the rs8192678 PGC-1α polymorphism have previously been studied alongside polymorphisms in peroxisome proliferator-activated receptor delta (PPARD) and sirtuin 1 (SIRT1) in relation to Alzheimer's disease and were found not to be associated with AD in a Finnish case-control situation." (PMID 21595954, 2011). "While Eng’s anti-inflammatory effects have been documented in intervertebral disc degeneration (via NF-κB/MAPK suppression) and Alzheimer’s disease (through Nrf2 activation), our work provides the first evidence of its AMPK/SIRT1/PGC-1α axis activation in IBD." (PMID 40427406, 2025). "Sirtuins contains of SIRT1, SIRT3, and SIRT6 in saliva can be an extra technique for non-invasive intravital diagnosis of Alzheimer’s disease in elderly individuals." (PMID 39484071, 2024). "In the Alzheimer’s disease model, soluble β-amyloid peptide oligomers (AβOs) prevent the PGC-1α-SIRT1 interaction, thereby decreasing the level of nuclear PGC-1α and promoting irreversible neurodegeneration." (PMID 36429110, 2022). "Efforts are ongoing to reveal how Sirt1 can be used to treat diseases, such as alcoholic liver disease (ALD), Alzheimer's disease, and liver fibrosis." (PMID 32269528, 2020). "Studies have shown that in the brain of Alzheimer’s disease model rats induced by D-gal, DMY can regulate the SIRT1-mTOR signaling pathway by inhibiting miR-34a, and ultimately inhibit D-gal-induced hippocampal neuronal cell damage." (PMID 33192493, 2020). "As has been reported, activation of SIRT1 using RSV has protection against disorders of the nervous system, for example, brain ischemia reperfusion injury, Alzheimer's disease, Parkinson's disease, and traumatic CNS injury." (PMID 29081884, 2017). "For example, SIRT1 activators such as resveratrol have also been shown to exert neuroprotective function in rodent models of ALS and Alzheimer’s Disease (AD) and to promote neuronal survival." (PMID 27917895, 2016). "We discuss different functions and targets of SIRT1 and SIRT2 in a variety of neurodegenerative diseases including Alzheimer's disease (AD), Parkinson's disease (PD) and Huntington's Disease (HD)." (PMID 23417962, 2013).
Alzheimer disease (continued). "Indeed, in the prodrome of transgenic mouse models of Alzheimer's disease, fibrillar amyloid (beta) stimulates the nuclear translocation of microglial TFEB, in part through sirtuin 1 (SIRT1)‐mediated deacetylation of TFEB at K116." (PMID 37728021, 2023). "Additionally, one study showed that 12-week treadmill training also increased the protein levels of biogenesis regulators (SIRT1, PGC-1α, and TFAM) along with the reduction of beta-amyloid accumulation in the brain of Alzheimer’s disease rats model." (PMID 34440215, 2021). "SIRT1 suppresses β-amyloid production by activating the α-secretase gene ADAM10 and induces Notch signaling pathway, illustrating its potential in the treatment of Alzheimer’s disease." (PMID 32089065, 2020). "There is compelling evidence to support the fact that SIRT1 and SIRT2 are shuttled between the nucleus and cytoplasm and perform context-dependent functions in neurodegenerative diseases including Alzheimer’s disease (AD), Parkinson’s disease (PD), and Huntington’s disease (HD)." (PMID 33597872, 2020). "Recent studies have demonstrated that the SIRT1/PGC-1α signaling pathway exerts potential neuroprotective properties in neurodegenerative diseases such as Alzheimer’s disease, Parkinson’s disease 41], Huntington’s disease, acute stroke, chronic epilepsy, and status epilepticus." (PMID 31340436, 2019). "In addition, activation of SIRT1 has also been reported to reduce neuronal damage in EAE and to mediate neuroprotection in animal models of Alzheimer's disease and amyotorophic lateral sclerosis." (PMID 25136908, 2014). "Furthermore, SIRT1 activation by cystatin C could shift APP processing toward a non-amyloidogenic pathway in BMECs, providing a potential target for the treatment of Alzheimer’s disease." (PMID 39598406, 2024). "Similar to oleuropein, its aglycone also increased SIRT1 protein levels in 6-month-old TgCRND8 mice and in the neuronal cell line, N2a, treated with N-methyl-N′-nitro-N-nitrosoguanidine (MNNG), in in vivo and in vitro models of Alzheimer’s disease, respectively." (PMID 35883477, 2022). "Likewise, Nrf2 over-expression in astrocytes can protect neurons in a non-cell autonomous manner from 3-NP toxicity, while Sirt1 over-expression can delay axonal degeneration and counteract neurodegeneration in a mouse model of Alzheimer disease." (PMID 22384090, 2012). "Resveratrol is a non-flavonoid polyphenol that can induce neuroprotection in Alzheimer's disease and other cognitive disorders through modulating the CAMP/AMPK/SIRT1 pathway." (PMID 40718448, 2025). "SIRT1 deacetylase protects against neurodegeneration in models of Alzheimer’s disease as well as ALS, although enhancing SIRT1 activity by resveratrol did not affect functional improvement or increased longevity in an SOD1 mutant mouse model of ALS." (PMID 24312501, 2013).
Cognitive impairment (165 papers, 2012 to 2026). Abnormal cognition is characterized by deficits in thinking, reasoning, or remembering. "Taken together, our study revealed a Sirt1-CaMKIIα-tau signaling pathway underlying GBP-induced cognitive impairment in aged mice." (PMID 40969938, 2025). "A recent study reported that WBI induced a decrease in SIRT1 expression in the rat hippocampus, which was associated with cognitive impairment." (PMID 40508105, 2025). "OVX and AD caused significant cognitive impairment (p < 0.001), up-regulated miR-134a (p < 0.001), down-regulated SIRT-1, CREB, and BDNF protein expression (p < 0.001), and decreased antioxidant marker levels (p < 0.001) compared to the sham group." (PMID 39061398, 2024). "Another study demonstrated that the expression level of SIRT1 decreased after infection, but its activators can inhibit the release of inflammatory mediators, preventing neural injury and cognitive impairment caused by excessive inflammatory response." (PMID 39022312, 2024). "Anesthesia and surgery have been observed to cause morphological changes in microglia, increased synaptic phagocytosis, dendritic spine loss, and cognitive deficits that can be mitigated by the administration of SIRT1 agonists." (PMID 38622895, 2024). "The results of this study showed that there was a significant correlation between plasma SIRT1 and PD with cognitive impairment; furthermore, the whole-brain GM volume had diagnostic value for PD with cognitive impairment." (PMID 37718350, 2024). "This study was designed to investigate the diagnostic value of plasma SIRT1 levels and whole-brain gray matter (GM) volume in Parkinson’s disease (PD) patients with cognitive impairment." (PMID 37718350, 2024). "The combination of plasma SIRT1 levels and total GM volume had good diagnostic accuracy for PD with cognitive impairment." (PMID 37718350, 2024). "Together, these data reveal that linagliptin combated hippocampal oxidative stress and stimulated SIRT1/Nrf2/HO-1 axis, favorable events that are, at least partly, implicated in the improvement in cognitive deficits triggered by cadmium in animals." (PMID 37630980, 2023). "SIRT1 is crucial for cognitive function, and low levels are abnormally associated with the cognitive impairment of neurodegenerative disorders." (PMID 37592394, 2023). "Enriching the environment, resveratrol, and other treatments to increase SIRT1 levels or activate SIRT1 can ameliorate cognitive impairment caused by aging, stress, or ischemia." (PMID 37592394, 2023). "For example, overexpression of SIRT1 or pharmacological activation of SIRT1 appears to reduce Aβ production, oxidative stress, synapse loss, and cognitive impairment of AD mouse model." (PMID 37602729, 2023). "In conclusion, this research reveals that SIRT1 is a crucial regulatory protein in the emergence of cognitive impairment caused by chronic pain." (PMID 37592394, 2023). "Considering the impact of silent information regulator 1 (SIRT1) on synaptic plasticity, we explored the exact role of SIRT1 in cognitive impairment caused by chronic pain." (PMID 37592394, 2023). "Dietary control and physical activity ameliorate HFD-induced cognitive impairment and abnormal neurometabolism, which is associated with SIRT1-mediated NF-κB pathways and PGC-1α-BDNF pathways." (PMID 36999158, 2023). "Our findings indicated that diet control and/or swimming exercise improved HFD-induced cognitive impairment through antineuroinflammation, which was associated with activating the SIRT1-NF-κB and SIRT1-PGC-1α-BDNF pathways." (PMID 36999158, 2023). "Only weak associations between SIRT1 SNPs and arthritis, myocardial infarction, deafness, and cognitive impairment were determined." (PMID 35629418, 2022). "Studies have shown that Sirt1 knockout (Sirt1-KO) would cause cognitive impairment and defects in synaptic plasticity, but the brains of Sirt1-KO mice exhibited normal morphology." (PMID 35668361, 2022).
Cognitive impairment (continued). "Sirt-1 has been widely studied as a regulator of many cellular physiological and pathological processes It was also observed that Sirt-1 was associated with cognitive impairment in AD, and similar results were obtained in depression studies." (PMID 33834065, 2021). "In the present study, we found that SIRT1 deficiency was associated with prolonged cognitive impairment in developing mice following repeated sevoflurane exposure." (PMID 32148659, 2020). "Sirtuin1 (SIRT1) is a deacetylase protein that reported to mediate hippocampal neuronal apoptosis in mice and causing cognitive deficit." (PMID 30349449, 2018). "Thereby, the neuroprotection of SIRT1 and resveratrol and their interaction should be explored to act on preventing cognitive impairment in T2DM-associated cognitive dysfunction." (PMID 29164153, 2017). "Taken together, Sirt1-CaMKIIα signaling pathway could be a molecular mechanism underlying tau hyperphosphorylation associated with cognitive impairment in GBP-treated aged mice." (PMID 40969938, 2025). "Finally, we discussed the correlation between plasma SIRT1 levels and whole-brain GM volume and their diagnostic values in PD patients with cognitive impairment." (PMID 37718350, 2024). "Furthermore, the combination of plasma SIRT1 levels and the total GM volume had good diagnostic accuracy for PD with cognitive impairment." (PMID 37718350, 2024). "Furthermore, plasma SIRT1 levels had a significant positive correlation with GM volume in the whole brain, and ROC analysis confirmed that plasma SIRT1 levels and the total GM volume had good diagnostic accuracy for PD with cognitive impairment." (PMID 37718350, 2024). "By reducing synaptic plasticity injury, SIRT1 in glutaminergic neurons of the hippocampal CA1 area may ameliorate cognitive impairment caused by chronic pain." (PMID 37592394, 2023). "Reduced SIRT1 expression in hippocampus of SNI mice may induce cognitive impairment associated with chronic pain by mediating the impaired synaptic plasticity." (PMID 37592394, 2023). "Although few studies have examined the association between IR and cognitive impairment, we concluded that SIRT1 might contribute indirectly to improve cognition, because many of SIRT1's downstream regulators are involved in memory processes." (PMID 29164153, 2017). "Our results support the hypothesis that resveratrol could attenuate Pb-induced cognitive impairment which was associated with activating SIRT1 via modulation of oxidative stress." (PMID 28706491, 2017). "The purpose of this study was to explore the diagnostic value of plasma SIRT1 levels combined with total GM volume through receiver-operating characteristic (ROC) analysis in PD patients with cognitive impairment to find a better diagnostic index for PD patients with cognitive impairment." (PMID 37718350, 2024). "Thus, RSV’s protective effects against cognitive impairment may be linked to its influence on sirtuin pathways, particularly SIRT1, offering potential therapeutic insights for neurodegenerative diseases beyond AD, including VCID." (PMID 39199230, 2024). "Thus, the regulation role of SIRT1 on BDNF via different signaling pathways may be a potential mechanism by which SIRT1 improves cognitive impairment associated with chronic pain, which need to be further researched." (PMID 37592394, 2023). "In addition, researchers have found that SIRT1 is neuroprotective in AD models through the regulation of Aβ metabolism, and that its deletion causes increased tau acetylation, phosphorylation, and cognitive defects." (PMID 36770893, 2023). "Additionally, a decrement of SIRT1 in the brain is associated with cognitive impairment." (PMID 37887307, 2023). "A study has reported that RES improved locomotor and cognitive deficits and modulated SIRT1 and Lingo-1 in harmaline-induced essential tremor." (PMID 40718448, 2025).